RNU6-252P (RNA, U6 small nuclear 252, pseudogene)
Gene: Small nuclear RNA gene on chromosome 14 (21,113,639 to 21,113,745, reverse strand). Ensembl gene ENSG00000200102.
Homologues: Orthologues: chimpanzee U6 (99% identical), pig U6 (89% identical). Paralogues in human: RNU6-38P (87% identical), RNU6-41P (87% identical), RNU6-1011P (86% identical), RNU6-1078P (86% identical), RNU6-166P (86% identical), RNU6-17P (86% identical), RNU6-18P (86% identical), RNU6-25P (86% identical), RNU6-29P (86% identical), RNU6-33P (86% identical), RNU6-39P (86% identical), RNU6-7 (86% identical), and 1287 more.